PGAM1 (phosphoglycerate mutase 1)
Diseases named in the same sentence as PGAM1 in open-access papers (continued):
Sharing a sentence is not in itself a finding about the gene and the disease.
cancer (95 papers, 2010 to 2026). A tumor composed of atypical neoplastic, often pleomorphic cells that invade other tissues. "Studies have shown that PGAM1 is highly expressed in various cancers and is closely associated with tumor aggressiveness and metastasis." (PMID 39990664, 2025). "It was found that PGAM1 expression was associated with various ICGs in different cancer types, but the direction and strength of the association varied." (PMID 38434965, 2024). "Overexpression of PGAM1 has been found in various human cancers, and increased expression of PGAM1 is associated with poor prognosis in cancer patients." (PMID 38773094, 2024). "The results showed that in most TCGA cancers, PGAM1 expression positively correlated with infiltration levels of macrophages, natural killer cells, myeloid dendritic cells, monocytes, cancer-associated fibroblasts, mast cells and neutrophils." (PMID 38434965, 2024). "We subsequently explored the association of PGAM1 mutations with common cancer progression genes, such as VHL, PBRM1, and SETD2." (PMID 37847178, 2023). "In cancer biology, PGAM1 has garnered attention due to its association with tumorigenesis, tumor progression, and therapeutic resistance." (PMID 37338518, 2023). "In cancer cells, PGAM1 is highly up regulated that cause rapid production of cancer cells and tumor growth." (PMID 37051414, 2023). "It has been reported that Pgam1 has a role in tumorigenesis and cellular aging, and Pgam1 has been suggested as a therapeutic target for age-associated diseases including cancer." (PMID 35521515, 2022). "PGAM1 plays an important role in anabolic activity to promote the proliferation of cells in cancer and contributes to the development of tumor associated with the glycolysis, and it is used as a therapeutic target potential." (PMID 34195264, 2021). "Overexpression of PGAM1 is linked with tumor growth, survival, and invasion in several cancers including GBM." (PMID 35004842, 2021). "Recent literature has documented that dysregulated PGAM1 expression is associated with tumorigenesis in various cancers." (PMID 32855383, 2020). "Since PGAM1 converts 3-phosphoglycerate into 2-phosphoglycerate in glycolysis, an increase in the activity of this enzyme in cancer cells causes a decrease in 3-phosphoglycerate." (PMID 33425906, 2020). "Recent studies have revealed that Pgam1 is upregulated in several human cancers and linked to the tumor growth and survival." (PMID 32709928, 2020). "Upregulation of PGAM1 is implicated in the development of many cancers, including hepatocellular carcinoma and colorectal cancer." (PMID 28076845, 2017). "However, the molecular mechanisms underlying the dysregulated expression of PGAM1 in cancer cells remain largely unclear." (PMID 38773094, 2024). "PGAM1 was determined to be a risk factor in most cancer types based on these analyses." (PMID 38434965, 2024). "Additionally, scRNA-seq revealed that loss of MUC1-C results in marked suppression of PGAM1, which is essential for glycolytic flux and anabolic pathways of nucleotide and amino acid synthesis necessary for cancer cell biogenesis." (PMID 37915591, 2023). "Therefore, while SEC61G and PGAM1 have been implicated in promoting tumor progression in various cancers, their specific roles and interactions in NSCLC brain metastases remain unclear." (PMID 39990664, 2025). "Correlation analysis shows PGAM1 expression correlates with infiltration levels of various immune cells including macrophages, natural killer cells, myeloid dendritic cells, monocytes, cancer-associated fibroblasts, mast cells, neutrophils, B cells, CD4+ T cells, CD8+ T cells and regulatory T cells." (PMID 38434965, 2024). "Additionally, PGAM1 could serve as an important diagnostic and therapeutic target for treating patients with cancer." (PMID 37542027, 2023).
cancer (continued). "Phosphoglycerate mutase 1 (PGAM1) is an important glycolytic enzyme that plays a significant role in cancer metabolism." (PMID 42116375, 2026). "PGAM1 enhances cancer cell proliferation and invasion by upregulating TGF-β signalling, contributing to tumour progression and EMT." (PMID 41154605, 2025). "The relationship between PGAM1 expression nd immune cell infiltration was investigated to demonstrate the link between PGAM1 and cancer immunity." (PMID 38434965, 2024). "This underscores PGAM1's role in cell motility and metastasis, providing a broader understanding of its impact in cancer biology." (PMID 38434965, 2024). "PGAM1 Y119 phosphorylation is triggered by growth factors’ signaling, that is usually constitutively activated in many cancers and important for tumor growth." (PMID 38750259, 2024). "In order to elucidate the expression pattern of PGAM1 in pan-cancer, we analyzed the TCGA_GTEx datasets of 33 tumors collected from TCGA-GTEx." (PMID 38434965, 2024). "This study performed a comprehensive analysis of PGAM1 expression across 33 cancer types in multiple public databases." (PMID 38434965, 2024). "As a key enzyme of glycolysis, the abnormal activation of PGAM1 is closely related to the occurrence and development of various malignant tumors." (PMID 38434965, 2024). "Overexpression of PGAM1 promotes cancer progression, whereas inhibition of PGAM1 using shRNAs or inhibitors effectively suppresses cancer progression." (PMID 38773094, 2024). "Collectively, this study reveals PGAM1 as a valuable prognostic biomarker and potential therapeutic target in aggressive cancers including UVM." (PMID 38434965, 2024). "The glycolytic enzyme PGAM1 plays a critical role in cancer metabolism by coordinating glycolysis and biosynthesis to promote rapid tumor growth." (PMID 38773094, 2024). "Correlation analysis showed that PGAM1 was widely and positively correlated with a variety of cancer-promoting immune cells such as TAMs, NK cells, and mDCs." (PMID 38434965, 2024). "Next, we injected DU145-luc in male nude mice via the tail vein to determine the correlation between PCa-derived exosomal PGAM1 and cancer metastasis." (PMID 37542027, 2023). "While PGAM1 is primarily known for its metabolic function, emerging research has revealed its significance in cancer biology and immunology, highlighting its multifaceted roles in these fields." (PMID 37338518, 2023). "The significance of PGAM1 in cancer biology and immunology suggests its potential as a therapeutic target." (PMID 37338518, 2023). "PGAM1 plays a critical role in cancer metabolism by critically catalyzing the conversion of 3‐PG to 2‐PG during aerobic glycolysis, which regulates intermediates used as precursors for anabolic biosynthesis." (PMID 37705495, 2023). "Numerous studies have demonstrated that PGAM1 is frequently activated in glycolysis and highly expressed in various types of cancer, including KIRC." (PMID 37847178, 2023). "Recent studies have demonstrated aberrant expression of PGAM1 in various cancers, including HCC, and its association with poor clinical outcomes, implying the potential role of PGAM1 in cancer development." (PMID 38093528, 2023). "Increasing evidence supports that aberrant expression of PGAM1 in several cancers promotes tumor growth and progression." (PMID 37501157, 2023). "Glycolytic enzyme phosphoglycerate mutase 1 (PGAM1) has potential stimulating roles in a number of human cancers." (PMID 37051414, 2023). "We also revealed that the genes with relatively high expression at 0 h were primarily related to cell growth and proliferation, particularly cancer cell proliferation, such as Tfap4, Rdm1, Ddx39b, Pgam1, and so on." (PMID 36834727, 2023). "PGAM1 plays a critical role in cancer cell metabolism through glycolysis and different biosynthesis pathways to promote cancer." (PMID 37051414, 2023).
cancer (continued). "The dysregulation of PGAM enzymes, particularly PGAM1, plays a significant role in cancer cell metabolism and proliferation, making them attractive targets for cancer therapy." (PMID 37847178, 2023). "As a consequence, PGAM1 activity and cellular glycolytic activity were lowered which contributed to inhibition of cancer progression." (PMID 38213532, 2023). "A glycolysis enzyme with an extensively studied group of inhibitors with potential anti-cancer activity is phosphoglycerate mutase 1 (PGAM1)." (PMID 35628385, 2022). "Phosphoglycerate mutant enzyme-1 (PGAM1) is a glycolytic gene that can promote the conversion of 3-phosphoglycerate to 2-phosphoglycerate to glycolysis, which can promote cancer cell proliferation and survival." (PMID 36387908, 2022). "Previous evidence has shown that the expression levels of PGAM1 are related to prognosis in many types of cancers." (PMID 35674458, 2022). "Among the known PGAM-1 and -2, PGAM-1 is deeply involved in cancer metabolic pathway, as deduced from the previous result that homozygous Pgam1 KO mice are lethal at the embryonic state." (PMID 36077431, 2022). "To explore the role of PGAM1 in BC, we analyzed the expression levels of PGAM1 in tumor and non‐tumor control tissues from the Cancer Genome Atlas (TCGA) database." (PMID 35674458, 2022). "PGAM1 is highly expressed in several cancers found in lung, urothelial bladder, non-small-cell lung cancer and HCC." (PMID 36077431, 2022). "During aerobic glycolysis, PGAM1 plays a critical role in cancer cell metabolism by catalyzing the conversion of 3-phosphoglycerate (3PG) to 2-phosphoglycerate (2PG)." (PMID 34195264, 2021). "Indirectly, PGAM1 contributes to DNA repair activity in cancer cells by the upregulation of glycolysis and/or nucleotide synthesis." (PMID 33834022, 2021). "Elevated levels of PGAM1 are correlated with poor prognosis for NSCLC patients, and knockdown of PGAM1 suppresses aggressive cancer phenotypes as well as mTOR-mediated glycolysis and oncogenesis in NSCLC cells." (PMID 34689761, 2021). "PGAM1 is overexpressed in a wide range of cancers, thereby promoting cancer cell proliferation and tumor growth, so it is gradually becoming an attractive target." (PMID 34899321, 2021). "Although we previously reported that both PGAM-1 and -2 affect global glycolytic profile of cancers in vitro, in vivo glucose parameters were less affected both in the heterozygous knockout of Pgam1 and in Pgam2 transgenic mice." (PMID 33914812, 2021). "PGAM1 is overexpressed in various cancer tissues and plays an essential role in cancer progression and metastasis." (PMID 33430318, 2021). "Phosphoglycerate mutase 1 (PGAM1) plays a critical role in cancer by the conversion of 3PG to 2PG during glycolysis." (PMID 34195264, 2021). "PGAM1 regulates the proliferation of cancer cells in term of biosynthesis regulation, partly by regulating intracellular levels of its product 2-PG and 3-PG." (PMID 34899321, 2021). "Phosphoglycerate mutase 1 (PGAM1) is considered as a novel target for multiple types of cancer drugs for the upregulation in tumor, cell prefoliation, and cell migration." (PMID 34195264, 2021). "The results imply that level of PGAM1 expression was extremely sensitive towards the treatments that inhibited its ability to produce energy to nourish cancer cells thereby increased their vulnerability to the platinum drug." (PMID 33053689, 2020). "Previous studies have reported that CA9, EXTL2, PGAM1, and TYMS were dysregulated across multiple human cancers and intricately associated with tumorigenesis by functioning as key enzymes underlying metabolism." (PMID 33425725, 2020). "HSPA8 was associated with most of glycolytic genes like PGK1 (r = 0.21~0.79) and PGAM1(r = 0.17~0.80) across all cancer types (p < 0.05)." (PMID 32635458, 2020).
cancer (continued). "As an example, the upregulated expression of the glycolytic enzyme PGAM1 in many cancers and its impact on cancer prognosis make this enzyme an interesting therapeutic target." (PMID 33202866, 2020). "A previous study demonstrated that PGAM1, as a critical metabolic enzyme involved in glycolysis and biosynthesis, contributes to cancer progression by regulating cancer metabolism." (PMID 32855383, 2020). "Consistently, IHC staining of xenograft tumor tissues using TGF-β, BMP4, ICAM1 and VCAM1 antibodies indicated suppression of the TGF-β signaling pathway status in PGAM1 silencing cancer cells compared to that in the control group." (PMID 32855383, 2020). "Posttranslational modulations of PGAM1 such as Y26 phosphorylation and deacetylation of K100 would promote cancer cell proliferation and tumor growth." (PMID 30818883, 2019). "Since PGAM1 regulates both glycolysis and biosynthesis, developing inhibitors targeting PGAM1 is considered as a way of dual inhibition of catabolism and anabolism for cancer therapy." (PMID 30818883, 2019). "Here we designed and synthesized a series of new anthraquinone compounds and evaluated their biological activity on PGAM1 and cancer cell proliferation." (PMID 30818883, 2019). "Upregulation of phosphoglycerate mutase 1 (PGAM1) has been identified as one common phenomenon in a variety of cancers." (PMID 29890679, 2018). "High PGAM1 expression of cancer tissues was observed in 47.1% of the patients (107 of 227), while high pS6 level was observed in 41.4% of the patients (94 of 227)." (PMID 29362480, 2018). "Our results suggest that although some genes were commonly modulated (eg., MMP9 and PGAM1 were upregulated by both normal and cancer exosomes), the effects were significantly amplified by cancer exosomes in recipient cells." (PMID 30008265, 2018). "This study aims to understand how EGCG inhibits the enzymatic activity of PGAM1 and to further prove its potential in modulating cancer metabolism." (PMID 28611670, 2017). "Rapid growth and division of cancer cells depend critically on their capability of coordinating glycolysis and biosynthesis, in which PGAM1 plays a crucial role." (PMID 28076845, 2017). "The upregulated PGAM1 activity in cancer cells, which occurs in multiple types of cancer including breast cancer, hepatocellular carcinoma and colorectal cancer, in turn fulfills the requirement of energy and biomacromolecules of tumor growth." (PMID 28611670, 2017). "Glycolytic enzymes are therefore often upregulated in cancer cells, including PGAM1, the enzyme catalyzing the eighth step of glycolysis." (PMID 28076845, 2017). "As PGAM1 repression inhibited cancer cell growth and induced remarkable apoptotic cell death in vitro, we have particular interest to examine the potential function underlying PGAM1-shRNA-a mediated anti-tumor activity in vivo." (PMID 20403181, 2010). "In addition, HAT1 can promote glycolysis by catalyzing the succinylation of phosphoglycerate mutase 1 (PGAM1) on K99 in cancer cells, thereby promoting tumorigenesis." (PMID 40867281, 2025). "Various cancers secrete phosphoglycerate mutase 1 (PGAM1) within EVs." (PMID 40722712, 2025). "PGAM1 plays an essential role in tumor growth and is a promising target for cancer therapy." (PMID 41080753, 2025). "Notably, IDH1 mutations are established cancer drivers through oncometabolite production, while PGAM1 enhances cancer cell survival by regulating glycolysis and biosynthesis pathways." (PMID 40861812, 2025). "Phosphoglycerate mutase 1 (PGAM1) is a key enzyme regulating cancer glycolysis." (PMID 38434965, 2024). "Thus, PGAM1 interactions with immune cells likely influence the immunologic landscape of the tumor niche, impacting cancer development and therapy response." (PMID 38434965, 2024). "CTTPPPD may inhibit the activation of the TGF-β signaling pathway and reduce the proliferation and invasion of cancer cells by reducing the expression of PGAM1." (PMID 39275122, 2024).
cancer (continued). "In summary, our findings suggest PGAM1 may regulate cancer progression, prognosis, and treatment response by modulating immune cells in the tumor microenvironment." (PMID 38434965, 2024). "Using the CPTAC dataset, we found that phosphorylation of the PGAM1 S118 site was higher in cancers such as BRCA, COAD, and ccRCC compared to normal tissues, while phosphorylation of the PGAM1 S31 site was higher in cancers such as PAAD, LUSC, LUAD, HNSC and HCC compared to normal tissues." (PMID 38434965, 2024). "This could provide a reference for further study to explore the specific mechanism of PGAM1 in HCC or other cancers." (PMID 38835015, 2024). "Additionally, DSS, DFI, and PFI were assessed to evaluate the effects of PGAM1 on prognosis of various cancers." (PMID 38434965, 2024). "The overexpression of PGAM1 in cancer cells confers several advantages." (PMID 37338518, 2023). "Consequently, PGAM1 succinylation was reduced and the decreased level of glycolysis ultimately inhibited cancer progression." (PMID 38213532, 2023). "Mechanistically, PGAM1 overexpression in KIRC may be attributed to metabolic abnormalities or the high energy requirements of metastatic cancer cells, as PGAM1 and HIF1A exhibit direct regulation." (PMID 37847178, 2023). "In KIRC, PGAM1 has been found to play a crucial role in tumor proliferation, and its high expression is associated with abnormal glycolysis and the formation of KIRC, making it a potential therapeutic target for cancer therapy." (PMID 37847178, 2023). "Phosphoglycerate mutase 1 (PGAM1) is involved in various cancer-related processes." (PMID 37542027, 2023). "Additionally, PGAM1 increased invadopodia formation in PCa cells, thereby triggering a series of events leading to cancer cell metastasis." (PMID 37542027, 2023). "Additionally, PGAM1 enhances the resistance of cancer cells to oxidative stress and apoptosis, enabling their survival and contributing to chemoresistance." (PMID 37338518, 2023). "Previous studies have shown that PGAM1 promotes cancer progression by inducing angiogenesis." (PMID 37542027, 2023). "PGAM1 knockdown suppresses glycolysis and cancer genesis due to oncogenic mTOR signaling." (PMID 35674458, 2022). "Moreover, the expression level of PGAM1 was negatively correlated with the prognosis of cancer patients and positively correlated with tumor stage and pathological grade in HCC, bladder cancer, and lung cancer." (PMID 36230492, 2022). "Hence, PGAM1 is considered to be a targeting role in the cancer therapeutic strategy and inhibited the overexpression of different types of cancer." (PMID 34195264, 2021). "In addition, PGAM1 is overexpressed in multiple cancers, including ovarian cancer, non–small-cell lung cancer (NSCLC), colorectal cancer, pancreatic ductal adenocarcinoma (PDAC), prostate cancer (PCa), and glioma." (PMID 34899321, 2021). "Phosphoglycerate mutase 1 (PGAM1) is an important glycolytic enzyme that regulates many important biological processes, such as glycolysis, the pentose phosphate pathway and serine biosynthesis in cancer cells." (PMID 32095334, 2020). "Thus, while PGAM1 activation improves HRR, PGAM1 inhibition sensitizes cancer cells to PARP inhibition by promoting a so-called “HR-ness” phenotype." (PMID 33202866, 2020). "PGAM1 catalyzes the conversion between 3-phosphoglyceric acid and 2-phosphoglyceric acid which regulates the glycolytic pathway and is also involved in multiple cancer processes." (PMID 31936222, 2020). "Given the potential tumor suppressive role of miR-3614-5p in cancer, we further explored whether PGAM1 mediated the tumor suppressive role of miR-3614-5p in NSCLC." (PMID 32855383, 2020). "In addition, PGAM1 counteracted the decrease in cancer cell metastasis potential induced by ectopic expression of miR-3614-5p, as revealed by the transwell and migration assay." (PMID 32855383, 2020). "Recently, more functions of PGAM1 in cancer metabolism were described." (PMID 30818883, 2019).